RICTOR (RPTOR independent companion of MTOR complex 2)
Diseases named in the same sentence as RICTOR in open-access papers (continued):
Sharing a sentence is not in itself a finding about the gene and the disease.
tumor (continued). "Our results suggested that XIAP, RICTOR and HDAC2 either independently or cooperatively contribute functionally to the tumour suppressive effects of miR-500a-5p in CRC cells." (PMID 30737378, 2019). "Consistently, they observed increased RICTOR expression and extent of AKT phosphorylation on serine 473 only in tumor cells." (PMID 30662577, 2018). "Consistently, similar results were observed in the staining of proliferating cell nuclear antigen (PCNA), RICTOR and VEGFA in these tumor tissues." (PMID 28030804, 2017). "Finally, Indian patient tumor tissues with high RICTOR expression also manifest high UGCG and ZFX expression, emphasizing the role of mTORC2-regulated ganglioside metabolism in tumor development." (PMID 40934285, 2025). "This further suggests that PI3K pathway alterations are a frequent molecular event in TNBC and that the respective contributions of RICTOR, PIK3CA, and PTEN to mTOR hyperactivation may drive tumor progression." (PMID 40019775, 2025). "Additionally, in vivo experiments further confirmed that RICTOR knockdown effectively negated the impact of KLF4 silencing, as evident from weekly tumor volume measurements and final tumor weight determinations." (PMID 39000273, 2024). "Moreover, we detected five different gene amplifications in two different tumor specimens, including MYC (n = 2), PDGFRA, KIT, KRAS, and RICTOR." (PMID 35454843, 2022). "Therapeutic resistance is one of the characteristics of tumor stemness, so we next explored whether the “RNA–RNA” crosstalk of HMGB1 and RICTOR can influence the therapeutic response of HCC." (PMID 34916485, 2021). "Moreover, we detected 15 gene amplifications in six different tumor specimens, including AR, CCND1 (n = 2), FGF19 (n = 2), FGF3 (n =2), KRAS (n = 2), MYC (n = 2), CCND3, CCNE1, CDK6, and RICTOR." (PMID 33203166, 2020). "Our in vivo data using the H1792 xenograft model showed single agent selumetinib had enhanced anti-tumor effects compared to mTORC1/2 inhibitor AZD2014, suggesting that mutKRASG12C is more sensitive to MEK1/2 inhibition than mTORC1/2, despite having RICTOR amplification." (PMID 30338041, 2018). "However, an increase in the number of CNA events was observed from low‐grade to high‐grade tumours, especially for concomitant gains of TERT, SDHA and RICTOR located on the p‐arm of chromosome 5." (PMID 27873319, 2017). "Therefore, AKT/RICTOR-mediated phosphorylation of DNMT1 and/or KDM5A regulates gene expression, including that of UGCG, leading to an increase in glucosylceramides and enhanced tumor progression." (PMID 40934285, 2025). "Moreover, the proteomic analysis of SN-MM cell lines revealed that RICTOR, a subunit of mTORC2 complex, is the most significantly activated upstream regulator, suggesting a relevant role for the PI3K-Akt-mTOR pathway in these neoplasms." (PMID 38191367, 2024). "Similarly, RRM2B (nucleotide biosynthesis), PRKAA1 (AMPK signaling), and RICTOR (mTOR signaling) had widespread copy number gains exclusively in glycolytic cancers, apart from RRM2B, which had copy number gains in ~30% of evaluated PRAD patient tumor genes." (PMID 36831501, 2023). "Interestingly, WDR59 and RICTOR KOs showed strong decrease in rpS6 phosphorylation levels, compared with non-targeting tumor samples." (PMID 34031411, 2021). "However, RICTOR activation is linked to resistance to receptor tyrosine kinase inhibitors and RICTOR interacts with EGFR independent of its kinase activity in other tumor entities." (PMID 34771501, 2021). "Notably, RICTOR expression, a defining component of the alternative mTORC2 complex, remained unchanged, highlighting a selective activation of mTORC1 rather than mTORC2 in response to food scarcity-induced tumor adaptation." (PMID 40887471, 2025).
tumor (continued). "Thus, to assess their functional relevance and contribution to TNBC tumor formation, we used a CRISPR/Cas9 KO approach to specifically block expression of one identified representative hit for each of the mTORC2 and GATOR2 complexes (RICTOR and WDR59, respectively) in the SUM159 cell line." (PMID 34031411, 2021). "Interestingly, the expression level of PTEN, a classical tumor suppressor and the most important PI3K pathway homeostatic regulator, was found slightly downregulated and in reciprocal correlation with the levels of RICTOR, an important scaffold of mTORC2 complex." (PMID 33092114, 2020). "Thus, it was proposed that this positive feedback would be significantly enhanced in the amplification of RICTOR, leading to the constant activation of AKT; this process is independent of upstream signals, and ultimately results in tumor progression and drug resistance." (PMID 32041519, 2020).
adenocarcinoma (2 papers, 2020 to 2024). A common cancer characterized by the presence of malignant glandular cells. "RICTOR amplification has been described in 10% of NSCLCs, and mutations in the tumor suppressor genes PTEN and STK11, which are negative regulators of mTOR signaling, have also been observed in squamous cell and adenocarcinomas." (PMID 38515456, 2024).
RICTOR also shares sentences with these, for which no sentence is quoted: squamous cell lung carcinoma (4 papers); metabolic disease (3); endometrial carcinoma (2); gastric adenocarcinoma (2); infection (2); kidney diseases (2); nasopharyngeal carcinoma (2); Allergy (1); Alpha-thalassemia (1); ampullary cancer (1); angiosarcoma (1); Anxiety (1); aortic aneurysm (1); asthma (1); autism (1); autoimmune disease (1); autoimmune disorders (1); brain cancer (1); cardiomyopathy (1); childhood ovarian dysgerminoma (1); Cognitive impairment (1); colon adenocarcinoma (1); dementia (1); diabetic retinopathy (1); digestive tumor (1); endocrine system disorder (1); epilepsy (1); gallbladder adenocarcinoma (1); head and neck squamous cell carcinoma (1); heart disease (1).
A further 23 diseases each share a sentence with RICTOR in 1 paper.